HTRA2 (HtrA serine peptidase 2)
Diseases named in the same sentence as HTRA2 in open-access papers (continued):
Sharing a sentence is not in itself a finding about the gene and the disease.
cytomegalovirus infection (2 papers, 2008 to 2021). A herpesvirus infection caused by Cytomegalovirus. "Cytomegalovirus infection is controlled by the evolutionarily ancient mitochondrial serine protease, HtrA2/Omi." (PMID 18769594, 2008). "In an effort to define viral and cellular contributions to morphological and biochemical events that terminate CMV infection, we have discovered the key role of mitochondrial HtrA2/Omi and a novel cell death pathway." (PMID 18769594, 2008). "CMV infection is a unique setting that has unveiled a direct role for HtrA2/Omi in a caspase-independent cell death pathway analogous to apoptosis." (PMID 18769594, 2008). "Thus, ΔUL37x1 infection sensitizes to the prodeath impact of HtrA2/Omi, and vMIA controls HtrA2/Omi prodeath pathways during wt CMV infection." (PMID 18769594, 2008). "Mitochondrial HtrA2/Omi restrains MCMV replication, reminiscent of its role in restricting HCMV infection in fibroblasts via the induction of PCD." (PMID 34578288, 2021). "K181 titers were ~50- to 100-fold higher in Htra2/Omi−/− BMDM compared with WT cells, indicating that this serine protease restricts MCMV infection as it does HCMV infection." (PMID 34578288, 2021).
deafness (2 papers, 2021 to 2023). An inherited or acquired condition characterized by the complete loss of the ability to hear from one or both ears. "We targeted editing of the Htra2 gene and demonstrated that knockout of the Htra2 gene by the adeno-associated virus (AAV)-mediated CRISPR/Cas9 system could effectively prevent aminoglycoside-induced ototoxic deafness in mice." (PMID 38259515, 2023). "Here, we develop CRISPR/Cas9 strategies to prevent aminoglycoside-induced deafness, a common type of acquired non-inherited sensorineural hearing loss, via disrupting the Htra2 gene in the inner ear which is involved in apoptosis but has not been investigated in cochlear hair cell protection." (PMID 33752742, 2021).
glioma (2 papers, 2015 to 2017). A benign or malignant brain and spinal cord tumor that arises from glial cells (astrocytes, oligodendrocytes, ependymal cells). "In addition, it was proposed that the interaction between NG2 and OMI/HtrA2, a mitochondrial serine released from damaged mitochondria in response to stress, also contributes to the elevated chemo- and radioresistance of gliomas." (PMID 29246031, 2017).
Huntington disease (2 papers, 2013 to 2022). Huntington disease (HD) is a rare neurodegenerative disorder of the central nervous system characterized by unwanted choreatic movements, behavioral and psychiatric disturbances and dementia. "Other top models were the mitochondrial gene HTRA2 knockout (that is lethal in adulthood), a modified acetylcholinesterase, a Huntington’s disease model, and the CRTC1 knockout." (PMID 34997033, 2022).
injury (2 papers, 2016 to 2019). Damage inflicted on the body as the direct or indirect result of an external force, with or without disruption of structural continuity. "HtrA serine peptidase 2 (HtrA2), also named Omi, is a pro-apoptotic protein that exhibits dramatic changes in expression levels in a variety of disorders, including ischemia/reperfusion injury, cancer, and neurodegeneration." (PMID 26784188, 2016).
leukemia (2 papers, 2015 to 2019). A malignant (clonal) hematologic disorder, involving hematopoietic stem cells and characterized by the presence of primitive or atypical myeloid or lymphoid cells in the bone marrow and the blood. "Notably, we provide the first evidence to demonstrate that CUR alone, and especially in combination with BUS, increased the expression of proapoptotic serine protease HTRA-2 in leukemia cells, particularly in leukemia stem-like cells." (PMID 26557682, 2015). "Test compounds induced apoptosis in chronic myelogenous (K562) and acute lymphoblastic (MOLT-4) leukemia cells by activation of receptor and mitochondrial apoptotic pathways and increased the expression of proapoptotic genes (BAX, NOXA, HTRA2, TNFRSF10B, ESRRBL1)." (PMID 31487824, 2019).
lung adenocarcinoma (2 papers, 2016 to 2022). A carcinoma that arises from the lung and is characterized by the presence of malignant glandular epithelial cells. "MPV17L can protect against mitochondrial oxidative stress and apoptosis by activation of Omi/HtrA2 protease, and its methylation has been shown to be associated with the prognosis of lung adenocarcinoma." (PMID 35681424, 2022). "For instance, Omi/HtrA2 expression is elevated in lung adenocarcinoma, hepatocellular carcinoma, and squamous cell carcinoma of the head and neck." (PMID 26784188, 2016).
melanoma (2 papers, 2025). A malignant, usually aggressive tumor composed of atypical, neoplastic melanocytes. "Notably, cleaved livin, upon interaction with HTRA2, relinquishes its anti-apoptotic function and assumes pro-apoptotic effects in melanoma cells." (PMID 40860809, 2025). "Furthermore, the co-expression of HTRA2 in TIG3-expressing melanoma cells counteracts TIG3-induced apoptosis." (PMID 40722819, 2025).
metastatic disease (2 papers, 2020 to 2023). "Our results confirmed the intracellular location of HtrA2 and showed that, in CRC tissue, the HtrA2 protein level was significantly decreased when compared to the unchanged colorectal mucosa, especially in tumors from patients with metastatic disease (combined stages III and IV)." (PMID 32486357, 2020). "Among the selected candidates, MUC4 was significantly up-regulated in both primary and metastatic samples of fast-progressing patients, whereas HTRA2 and RAB25 were significantly elevated only in primary samples and EPCAM only in metastatic tumors of the fast-progressing group." (PMID 36527824, 2023).
motor neuron degeneration (2 papers, 2016 to 2021). "The study also suggested Omi/HtrA2 protease as a negative regulator of MUL1, since it accumulated in Omi/HtrA2(−/−) MEFs and in different tissues of motor neuron degeneration-2 (mnd2) mutant mice." (PMID 35011599, 2021).
myocardial infarct (2 papers, 2016 to 2019). "Furthermore, preventing HtrA2-induced apoptosis in animal models using a specific HtrA2 inhibitor (UCF-101), resulting in a decrease of myocardial infarct size and better outcome of cardiac contractility function." (PMID 31683713, 2019).
neuroblastoma (2 papers, 2019 to 2024). Neuroblastoma (NB) is the most common solid, extracranial childhood tumor. "Similarly, treatment of differentiated neuroblastoma cells and human primary neurons with interleukine-1β increases the release of OMI/HTRA2 from mitochondria, accompanied by increased OMI/HTRA2 protease activity." (PMID 30361890, 2019). "This positive correlation in turn may indicate a close mechanistic link between these two stress-related proteins, OMI/HTRA2 and AChE-R, since an increase in OMI/HTRA2 protease activity is reported after stress condition in differentiated neuroblastoma cells and in the AD brain." (PMID 30361890, 2019).
neutropenia (2 papers, 2017). A decrease in the number of neutrophils found in the blood. "Here we report two additional unrelated, consanguineous families in which the affected children carried novel bi-allelic pathogenic variants in the HTRA2 gene, leading to 3-MGA-uria, seizures, hypotonia, neutropenia and cardio-respiratory difficulties." (PMID 27696117, 2017).
Tremor (2 papers, 2017 to 2020). An unintentional, oscillating to-and-fro muscle movement about a joint axis. "Adult onset has been associated with dominant HTRA2 variants inducing tremor, while recessive variants cause adult onset Parkinson’s disease and infants with recessively inherited seizures, dysphagia, hypotonia, apnea, and cataracts." (PMID 33426505, 2020).
3-Methylglutaric aciduria (1 paper, 2024). An abnormally increased level of 3-hydroxy-3-methylglutaric acid in the urine. "3-methylglutaric aciduria is an autosomal recessive inherited metabolic disorder caused by defects in the HTRA2 gene." (PMID 40217354, 2024).
acute pneumonia (1 paper, 2024). "In addition, inhibition of HtrA2 attenuated the lipopolysaccharide-induced inflammatory response and apoptosis in acute pneumonia in rats, suggesting that HtrA2/Omi changes act as inflammatory signaling factors involved in the SCI response process." (PMID 38338855, 2024). "In addition, HtrA2/Omi was released from mitochondria to the cytoplasm in pneumonia." (PMID 38338855, 2024).
age (1 paper, 2018). A temporal measurement of the time period elapsed since an identifiable point in the life cycle of an organism. "In conclusion, these results suggest that Omi/HtrA2 participates in age-related autophagic deficiency in rat liver." (PMID 30574416, 2018).
Allergy (1 paper, 2020). An allergy is an immune response or reaction to substances that are usually not harmful. "Nevertheless, while in CM as in a lymphoproliferative disorder, the release of HTRA2 from abnormal MCs into extracellular space (ECS) might be expected; the reason why HTRA2 is assessed in serum in higher amounts than in controls in allergy remains unclear." (PMID 32560402, 2020).
amyotrophic lateral sclerosis (1 paper, 2021). Amyotrophic lateral sclerosis (ALS) is a neurodegenerative disease characterized by progressive muscular paralysis reflecting degeneration of motor neurons in the primary motor cortex, corticospinal tracts, brainstem and spinal cord. "In addition, abnormal accumulations of HtrA2/Omi exhibit in several types of motor neuronal inclusions, associating with the pathogenesis of amyotrophic lateral sclerosis." (PMID 34677809, 2021).
Ataxia (1 paper, 2014). Ataxia refers to impaired coordination of voluntary muscle movement. "HTRA2 KO mice went on to demonstrate a progressively worsening phenotype, initially presenting at around P25 as uncoordinated movement, progressing into ataxia, loss of balance, rolling and tremors followed by lethargy." (PMID 25531304, 2014). "We found that mice with neural-specific deletion of Htra2 exhibited atrophy of the thymus and spleen, cessation to gain weight past postnatal (P) day 18, neurological symptoms including ataxia and complete penetrance of premature death by P40." (PMID 25531304, 2014).
bipolar disorder (1 paper, 2017). A disorder of the brain that causes unusual shifts in mood, energy, activity levels and the ability to carry out day-to-day tasks. "This gene list includes new excellent candidates with putative links to bipolar disorder, including ADK, GTF2I, hnRNP-A1, HTRA2, PKD1 and RERE, which have been linked to various brain-related diseases." (PMID 28915787, 2017).
bladder transitional cell carcinoma (1 paper, 2021). The most common morphologic subtype of urinary bladder carcinoma (over 90% of cases). "Previous studies showed HTRA2 displayed a correlation to the development of various carcinoma, such as bladder transitional cell carcinoma and colon carcinoma." (PMID 34708890, 2021).
cardiomyopathy (1 paper, 2022). A disease of the heart muscle or myocardium proper. "Thus, an imbalance of HTRA2 levels appears to be associated with cardiomyopathy." (PMID 35328774, 2022). "Genes important in these processes and that are associated with cardiomyopathy include DNAJC19, MAGMAS, TIMM50, MIPEP, XPNPEP3, HTRA2, CLPB and HSPD1." (PMID 35328774, 2022). "Several of the disorders associated with cardiomyopathy involve genes important for preprotein processing, such as MIPEP, XPNPEP3, CLPB, and HTRA2." (PMID 35328774, 2022).
chronic heart failure (1 paper, 2022). "However, mice with a cardiac-specific overexpression of HTRA2 have DCM, while elevated HTRA2 was reported in the left ventricle of dogs with chronic heart failure." (PMID 35328774, 2022).
colorectal adenocarcinoma (1 paper, 2019). The most common type of colorectal carcinoma. "To find the mechanism by which HtrA2 regulates necroptosis, we treated HT-29, a type of colorectal adenocarcinoma cell, with TNF-α plus Smac mimetic and Z-VAD (T/S/Z) in vitro." (PMID 31019191, 2019).
Colorectal Tumors (1 paper, 2020). "In the present study we evaluated the expression of the HTRA1-3 genes, encoding human HtrA serine proteases HtrA1, HtrA2, and HtrA3 isoforms (HtrA3L and HtrA3S), at both mRNA and protein levels, in colorectal tumor tissue and unchanged colorectal mucosa of the CRC patients." (PMID 32486357, 2020). "Of the analyzed cases, 61 % of colorectal tumors had lower level of HtrA1 when compared to corresponding colorectal mucosa, whereas the HtrA2 protein level was lower in 71 % of the tumors." (PMID 32486357, 2020). "Thus, the protease seems to be an important player that attenuates the metastatic potential of cancer cells, and the observed reduction in HtrA2 protein level in colorectal tumors could promote cancer development and dissemination." (PMID 32486357, 2020).
depression (1 paper, 2022). "Seven models that matched depression from different approaches (HDAC2 forebrain KO, APPsa knockin, stress portrait, ACHE variant, HD R6/1 transgenic, CRTC1 KO, and HTRA2 KO) were analyzed and common up and down regulated genes with depression were identified." (PMID 34997033, 2022). "The HTRA2 KO it is lethal in adulthood and that may limit its usefulness for understanding depression." (PMID 34997033, 2022).
endometrial cancer (1 paper, 2015). Primary or metastatic malignant neoplasm involving the endometrium (mucous membrane that lines the endometrial cavity). "Narkiewicz and colleagues studied HtrA1, HtrA2 and HtrA3 mRNA and protein by two semi-quantitative techniques, RT-PCR (mRNA) and WB (protein), in 124 women; 88 with endometrial cancer and 36 with normal endometrium." (PMID 26035313, 2015).
Failure to thrive (1 paper, 2014). Failure to thrive (FTT) refers to a child whose physical growth is substantially below the norm. "Systemic deletion or mutation of HTRA2 in mice causes neurological phenotypes, lymphopenia and a failure to thrive." (PMID 25531304, 2014). "Additionally by P19, close to the time when the failure to thrive begins, HTRA2-deficient pups display markedly reduced motor activity when compared to WT pups demonstrating that an observable motor phenotype is present before the development of an ataxic gait." (PMID 25531304, 2014).
fibrosarcoma (1 paper, 2023). A malignant mesenchymal fibroblastic neoplasm affecting the soft tissue and bone. "In an initial assessment of the role of HtrA2/Omi in parthanatos, we employed L929Ts fibrosarcoma cells, a cell system that we had successfully used in previous analyses of the molecular differences between parthanatos and necroptosis." (PMID 37594630, 2023).
hearing loss (1 paper, 2021). "Therefore, we selected Htra2 as the target gene and constructed CRISPR/Cas9–Htra2 knock out systems with the first aim of preventing aminoglycoside-induced hearing loss in mice." (PMID 33752742, 2021).
heart failure (1 paper, 2020). Inability of the heart to pump blood at an adequate rate to meet tissue metabolic requirements. "Later on, expression of LONP1 and HTRA2 was increased in mutant hearts, likely as a compensatory mechanism but still could not prevent mutant hearts from developing chamber dilation and heart failure in the end." (PMID 31209364, 2020).
hippocampal atrophy (1 paper, 2025). "Finally, immunofluorescence and magnetic resonance imaging (MRI) analysis revealed that HTRA2 downregulation resulted in hippocampal atrophy." (PMID 39794315, 2025).
hyperlipidemia (1 paper, 2016). "HtrA2 overexpression inhibited plaque development as well as the differentiation of Th17 in ApoE−/− mice after immunization with proteoglycans to induce a hyperlipidemia-based RA animal model." (PMID 28008946, 2016). "HtrA2 may have a remedial function of reducing plaque formation in the aorta and differentiation of Th17 in hyperlipidemia-based RA." (PMID 28008946, 2016). "As well, HtrA2 revealed curative activity in a CIA and hyperlipidemia-based RA." (PMID 28008946, 2016). "Finally, we examined whether HtrA2 inhibits the development of plaque and Th17 differentiation in APOE knockout mice immunized with a proteoglycan to induce a hyperlipidemia-based animal model of RA." (PMID 28008946, 2016).
Insulin resistance (1 paper, 2022). Increased resistance towards insulin, that is, diminished effectiveness of insulin in reducing blood glucose levels. "HFD + AAV8-TBG-mNeongreen mice exhibited impairment of glucose tolerance and insulin resistance, while HtrA2/Omi-injected mice displayed lower blood glucose." (PMID 35449197, 2022).
ischemic heart disease (1 paper, 2019). "Growing evidence indicates that HtrA2, a pro-apoptotic protein, is associated with myocardial reperfusion injury and that targeted anti-apoptotic treatments may improve clinical outcomes in patients with ischemic heart disease." (PMID 31683713, 2019).
kidney failure (1 paper, 2013). An acute or chronic condition that is characterized by the inability of the kidneys to adequately filter the blood. "With HtrA2/Omi and UCH-L1, we have also revealed two novel targets for therapeutic intervention, which may assist in developing strategies for the treatment of damage induced by necroptosis/programmed necrosis (e.g. in organs such as the kidney and the brain, caused by stroke or kidney failure)." (PMID 24090154, 2013).
left ventricular hypertrophy (1 paper, 2019). Enlargement of the LEFT VENTRICLE of the heart. "In accordance, transgenic htra2mnd2 mice with deficient HTRA2 activity show an obvious heart enlargement with left ventricular hypertrophy accompanied by decreased mitochondrial energy supply and decreased glucose metabolism." (PMID 31443184, 2019).
liver steatosis (1 paper, 2022). "In this study, we demonstrated that HtrA2/Omi decreased in the fatty liver, and restoration of HtrA2/Omi reduced hepatic steatosis." (PMID 35449197, 2022). "However, restoring HtrA2/Omi ameliorated hepatic steatosis, confirming by improved serum lipid profiles, glucose homeostasis, insulin resistance, histopathological lipid accumulation, and the gene expression related to lipid metabolism." (PMID 35449197, 2022). "In summary, we reported that HtrA2/Omi expression could greatly reduce liver steatosis, improve glucose tolerance and hepatic insulin resistance in a mouse model of HFD-induced NAFLD." (PMID 35449197, 2022).
lung carcinoma (1 paper, 2022). "Using a functional siRNA screen of PCD proteins, we identified HtrA2 as a positive mediator of radiation‐induced senescence in NCI‐H460 lung cancer cells, reflecting its ability to maintain sustained proliferation arrest over time." (PMID 35122388, 2022). "This suggests that HtrA2 (also known as Omi, see placement in PCD map), a mitochondrial Ser protease that is released to the cytosol during cell stress, may be a positive mediator of radiation‐induced senescence in NCI‐H460 lung cancer cells." (PMID 35122388, 2022).
lymphoid leukaemia (1 paper, 2022). "Similarly, there was a synergistic increase in the expression of HTRA2/OMI gene and protein in Jurkat lymphoid leukaemia cells when treated with all the combination treatments (P ≤ 0.05)." (PMID 35614109, 2022).
malaria (1 paper, 2022). Malaria is a serious and sometimes fatal disease caused by a parasite that commonly infects a certain type of mosquito which feeds on humans. "Here, we have identified a homolog of HtrA2 in the human malaria parasite P. falciparum (PfHtrA2) and carried out detailed localization, gene knock-down, and cellular functional analyses to understand its role in mitochondrial homeostasis." (PMID 36306288, 2022).
metastatic cancer (1 paper, 2020). A carcinoma which has spread from the original site of growth to another anatomic site. "A significant reduction of the HtrA2 protein level in the primary tumors from patients with metastatic cancer as compared to control non-malignant tissue was observed." (PMID 32486357, 2020).
motor neuron disease (1 paper, 2018). "In fact, Omi/HtrA2 knockout or transgenic mice possess a phenotype either reminiscent of PD or motor neuron disease, respectively." (PMID 30034773, 2018).